FASN (fatty acid synthase)
Diseases named in the same sentence as FASN in open-access papers (continued):
Sharing a sentence is not in itself a finding about the gene and the disease.
glioblastoma (28 papers, 2016 to 2026). The most malignant astrocytic tumor (WHO grade IV). "FASN also plays a key role in maintaining tumor stemness and accelerating tumor growth and invasion in glioblastoma." (PMID 40002387, 2025). "Elevated FASN expression in glioblastoma leads to increased production of FAs, which are essential components for membrane biogenesis, energy storage, and signaling molecules that promote tumor proliferation and survival." (PMID 40422872, 2025). "Inhibition of FASN has been shown to sensitize glioblastoma cells to chemotherapy, indicating its potential as a therapeutic target." (PMID 40422872, 2025). "Treating glioblastoma cells with FASN inhibitors, Orlistat, Cerulenin, and C75, induced autophagy and apoptosis, and reduced cell viability." (PMID 40097417, 2025). "Limited information is available regarding the effects of inhibiting the lipogenic enzyme fatty acid synthase (FASN) in glioblastoma (GB) cells (grade-IV-astrocytoma), which have high invasion and low response to standard treatments." (PMID 40133683, 2025). "Inhibition of FASN significantly enhances the radiosensitivity of glioblastoma cells, and combining FASN blockade with focal radiation therapy prolongs the survival of glioblastoma-tumor-bearing mice." (PMID 40097417, 2025). "FASN is essential for brain function, and its expression in glioblastoma is elevated to meet the lipid requirements of tumor." (PMID 40097417, 2025). "TVB-264, a FASN inhibitor, has entered phase II trials in glioblastoma and can be safely and effectively combined with bevacizumab." (PMID 40002387, 2025). "Further studies should investigate the effects of FASN inhibition on glioblastoma when combined with targeted therapies." (PMID 38672673, 2024). "FASN has been found to be upregulated in both glioblastoma cell lines and human glioma tissues compared with normal rat astrocytes and normal human brain, respectively." (PMID 38254886, 2024). "The lipid profiles of glioblastoma have demonstrated elevated FASN in glioma tissue and, specifically, in extracellular vesicles (EVs), including CD63- and CD8-positive glioblastoma EVs." (PMID 38539424, 2024). "FASN expression, typically correlated with glioblastoma aggressiveness, is a key player in lipid synthesis whose inhibition induced programmed cell death in cancer cells." (PMID 39334719, 2024). "Crocetin treatment suppresses fatty acid synthase (FASN) expression in glioblastoma cell lines (U251, U87MG, U373 and U138), activating apoptosis pathways, as evidenced by the presence of cleaved caspase-3 bands." (PMID 39334719, 2024). "Research has shown that the expression of FASN is upregulated in glioblastoma tumors compared to normal brain tissue." (PMID 37046844, 2023). "Inhibitors of FASN are known to impede glioblastoma cell growth, reduce cell viability, and inhibit the cell cycle, leading to apoptosis and necrosis of glioblastoma cells." (PMID 37046844, 2023). "In glioblastoma tumors, there is high expression of FASN and intensive production of fatty acids, which, in their free form or incorporated into phospholipids in cell membranes, can have a destructive effect on the cell’s lipid membrane structure." (PMID 37046844, 2023). "Due to the significant role of FASN in glioblastoma, FASN inhibitors have demonstrated antitumor properties in vitro and in vivo studies." (PMID 37046844, 2023). "Western blot results showed that the glioblastoma samples had high FASN and SREBP1c expression and low PER2 expression." (PMID 37069338, 2023). "Specifically, higher expression of FASN and increased de novo synthesis of fatty acids have been detected in glioblastoma cancer stem cells, which play a crucial role in the stemness and migration of these cells." (PMID 37046844, 2023). "For instance, the therapeutic targeting of FASN is currently being explored in a phase 2 clinical trial in patients with glioblastoma using the FASN inhibitor TVB-2640 in combination with bevacizumab (NCT03032484)." (PMID 36591531, 2022).
glioblastoma (continued). "We further found that total counts of double positive FASN+/CD63+ as well as FASN+/CD81+ EVs were significantly increased in the blood of glioblastoma patients, and the former was also significant in patients with anaplastic astrocytomas." (PMID 32178271, 2020). "We detected significantly elevated levels of FASN in glioblastoma and anaplastic astrocytoma tissue compared to normal brain." (PMID 32178271, 2020). "FASN is a protein that is frequently highly expressed in glioblastoma, and its expression relates to the malignance of the disease." (PMID 31936544, 2020). "The percentage of FASN+ EVs in glioblastoma patients was more than twice that of healthy donors (mean 16.5% GBM vs 7.1% HD, P = 0.007), with a similar result for patients with anaplastic astrocytomas (mean 18.8% AA vs 7.1% HD, P = 0.006)." (PMID 32178271, 2020). "In contrast, FASN was readily detectable in the vast majority of samples (14/17) collected from glioblastoma patients." (PMID 32178271, 2020). "Quantification of staining intensity confirmed a strikingly higher expression of FASN in glioblastomas than in normal brain (P < 0.01) and also in anaplastic astrocytomas compared to normal brain (P < 0.05)." (PMID 32178271, 2020). "FASN is overexpressed in various types of cancer including glioblastomas and is a potential therapeutic target." (PMID 32178271, 2020). "Significantly elevated levels of FASN were detected in glioblastoma tissue compared to control tissue by Western blot analysis." (PMID 32178271, 2020). "Consistent with our immunoblot analysis, the percentage of FASN-positive EVs was significantly elevated in patients with glioblastomas and anaplastic astrocytomas compared to controls." (PMID 32178271, 2020). "Further, a trend towards higher expression of FASN in glioblastomas than in anaplastic astrocytomas was observed (P < 0.1)." (PMID 32178271, 2020). "Tang and co-workers have shown that HSP60 silencing alter directly the expression of FASN and ACCα in glioblastoma cells." (PMID 29230177, 2017). "We also found that FASN expression was decreased by serum-induced differentiation, and that GSCs were more sensitive to FASN inhibition than glioblastoma cell lines." (PMID 26808816, 2016). "In this study, FASN was highly detected in the cytoplasm of human glioblastoma cells, and FASN was frequently co-localized with Sox2, a marker of GSC." (PMID 26808816, 2016). "Treatment of glioblastoma cells with FASN inhibitors resulted in a significant reduction in tumor cell viability." (PMID 27791206, 2016). "The results demonstrated for the first time that inhibiting FA production and FASN function induces cell death through ROS generation and ER stress while simultaneously reducing the motility and aggressiveness of U-87MG human glioblastoma cells by attenuating EMT and stemness phenotypes." (PMID 40133683, 2025). "Besides, since PI levels in glioblastoma tumors are higher than in healthy brain tissue, stopping FASN-mediated PI3K signaling increases the therapeutic importance of CER." (PMID 40133683, 2025). "The overexpression of FASN has been described in many tumor types, including glioblastomas." (PMID 38672673, 2024). "Therefore, FASN inhibitors have prolonged overall survival in mice with intracranial glioblastoma cells." (PMID 37046844, 2023). "Interestingly, FASN expression varies within glioblastoma tumors depending on the type of cancer cells present." (PMID 37046844, 2023). "Glioblastoma cancer stem cells have been found to secrete extracellular vesicles containing FASN, which are detectable in the blood of glioblastoma patients and, therefore, may serve as a disease marker." (PMID 37046844, 2023). "Further studies on the function of FASN in GSCs may provide insights into the contribution of fatty acid metabolism to the biology of glioblastoma." (PMID 26808816, 2016).
glioblastoma (continued). "Taken together, our results indicate that FASN plays a pivotal role in the maintenance of GSC stemness, and FASN-mediated de novo lipid biosynthesis is closely associated with tumor growth and invasion in glioblastoma." (PMID 26808816, 2016). "Additionally, FASN is involved in glioblastoma radio-resistance." (PMID 40097417, 2025). "Glioblastoma CSCs (GBM-CSCs) express high levels of fatty acid synthase (FASN), and inhibiting FASN reduces their proliferation and migration." (PMID 39456967, 2024). "Moreover, FASN expression is higher in glioblastoma tumors than in low-grade gliomas." (PMID 37046844, 2023). "Additionally, FASN inhibition reduces the growth and stemness of glioblastoma cancer stem cells." (PMID 37046844, 2023). "This evidence shows that FASN inhibition can attenuate CSC function by reducing clonogenicity, migration, and EMT markers in aggressive glioblastoma cells." (PMID 40133683, 2025). "Considering that the TVB‐2664 (inhibitor of FASN) and Myriocin (autophagy activator) have been used in several clinical trials, including nonalcoholic fatty liver disease (NAFLD) and glioblastoma, our results were inspiring." (PMID 40019378, 2025). "Inhibiting fatty acid synthase (FASN) enzyme has been shown to decrease lipogenesis, and as a result the expression of glioblastoma stem cell (GSC) markers such as CD133, SOX2, and nestin, as well as cell proliferation and migration." (PMID 37894287, 2023). "FASN promoted maintaining CSC stemness and was connected with cell proliferation and invasion ability in glioblastoma." (PMID 35047398, 2021). "This analysis confirmed that FASN was exclusively detectable in EVs from glioblastoma patients but not from healthy controls and was only detectable in the vesicle fraction but not in the void." (PMID 32178271, 2020). "Thereby we confirmed that FASN is exclusively detectable in in EVs from glioblastoma patients, but not healthy donors, and is only detectable in vesicles but not in the void fraction." (PMID 32178271, 2020). "To confirm and extend this finding, we immunostained tissue samples from glioblastomas (n = 15), anaplastic astrocytomas (n = 5) and non-tumorous brain (n = 3) for FASN." (PMID 32178271, 2020). "However, according to GEPIA, higher FASN expression does not affect patient prognosis in glioblastoma." (PMID 37046844, 2023). "Importantly, however, the total count of double positive FASN+/CD63+ EVs (mean 4.1 × 105/mL GBM vs 5.8 × 104/mL HD, P = 0.001) as well as the total count of FASN+/CD81+ EVs (mean 8.0 × 105/mL GBM vs 2.3 × 105/mL HD, P = 0.007) was significantly increased in the plasma of glioblastoma patients." (PMID 32178271, 2020).
non-small cell lung carcinoma (28 papers, 2013 to 2026). A group of at least three distinct histological types of lung cancer, including non-small cell squamous cell carcinoma, adenocarcinoma, and large cell carcinoma. "The current study was aimed to investigate the metabolic changes associated with FASN inhibition in non-small cell lung cancer (NSCLC) cell lines with various molecular genetic abnormalities that affect FASN expression activity levels." (PMID 22886728, 2013). "The current study was aimed to investigate the metabolic changes associated with FASN inhibition by orlistat and to understand the molecular mechanisms behind the observed metabolic changes in non-small cell lung carcinoma (NSCLC) cell lines." (PMID 22886728, 2013). "Furthermore, a recent study found that FASN mediates EGFR palmitoylation in EGFR-mutated chemo-resistant non-small cell lung cancer." (PMID 32792852, 2020). "In a recent study, it has been demonstrated that tyrosine kinase inhibitor (TKI) resistance in non-small cell lung cancer (NSCLC) could be caused by mutated epidermal growth factor receptor (EGFR) which uses the regulation of the fatty acid synthase (FASN) to induce TKI." (PMID 37328876, 2023). "The FASN inhibitor TVB-2640 has been used to treat non-small cell lung cancer and colon cancer in clinical studies." (PMID 37041584, 2023). "MiRNA-320 inhibits non-small cell lung cancer cell proliferation, migration, and invasion by targeting FASN." (PMID 37041584, 2023). "The fatty acid synthetic enzyme FASN induces EMT by enhancing TGF-β expression in non-small cell lung cancer." (PMID 32509584, 2020). "FASN-mediated palmitoylation of target proteins is recognized as a significant mechanism underlying resistance, particularly in TKI-resistant, epidermal growth factor receptor (EGFR)-mutated non-small cell lung cancer." (PMID 40149597, 2025). "Recent studies showed that TVB-3166—an orally available, reversible, potent, and selective FASN inhibitor—decreases viability in multiple tumor cell lines from solid and hematopoietic tumor types and tumor growth of patient-derived non-small-cell lung cancer xenograft tumors." (PMID 29872506, 2018). "Highly expressed FASN regulated by SREBP1 contributes to cancer malignancy and poor prognosis in non-small cell lung cancer." (PMID 38560498, 2024). "Christian F Ruiz's team found that mutant KRAS promotes the de novo lipid synthesis and the SREBP1-mediated mitochondrial gene expression in non-small cell lung cancer, and mutant KRAS tumor cells are susceptive to FASN inhibitors." (PMID 38560498, 2024). "In non-small cell lung cancer (NSCLC) cells with a mutant EGFR, FASN induces indirectly EGFR palmitoylation which prevents its inhibition by tyrosine kinase inhibitors (TKI)." (PMID 36934087, 2023). "TVB-2640 is a potent and reversible inhibitor of FASN and has been validated in a variety of tumor cell lines, including KRAS-mutant non-small cell lung cancer (NSCLC), colon cancer, advanced HER2 breast cancer, and glioblastoma, as well as in clinical studies." (PMID 39990210, 2025). "FASN and EMT are reciprocally and coordinately upregulated in non-small cell lung cancer." (PMID 32509584, 2020). "Stable knock down of FASN in non-obese diabetic/severe combined immunodeficiency (NOD/SCID) mice injected with A549 non-small cell lung cancer cells resulted in increased metastatic spread to lymph nodes, colon, liver and thymus and decreased overall survival." (PMID 29331414, 2018). "Consistently, in patients with resectable non-small-cell lung cancer (NSCLC), higher FASN activity in the cancer tissues (relative to the adjacent non-cancer lung tissue) was associated with adverse outcomes and predicts shorter patient survival." (PMID 24932311, 2014).
cervical cancer (25 papers, 2018 to 2026). A primary or metastatic malignant neoplasm involving the cervix. "For example, fatty acid synthase (FASN) is up-regulated in cervical cancer (CC), and it is associated with LN metastasis." (PMID 37803421, 2023). "Further studies are required to explore the biological functions and underlying molecular mechanisms of ERG and FASN in cervical cancer." (PMID 30237984, 2018). "The downregulation of Fatty acid synthase promotes ferroptosis, mainly by decreasing SLC7A11 in cervical cancer, and targeting FASN enhances cisplatin sensitivity in cervical cancer." (PMID 40438588, 2025). "Our results showed that RACK1 enhances de novo fatty acid synthesis by upregulating the expression of ACC1 and FASN, leading to lipid accumulation and promoting the proliferation of cervical cancer cells." (PMID 39425259, 2025). "For example, FASN facilitates lymph node metastasis in cervical cancer by modulating cholesterol reprogramming and then activating the lipid raft-related c-Src/AKT/FAK signaling pathway." (PMID 40148316, 2025). "ChIP assays were subsequently performed to further confirm that ACC1 and FASN were direct target genes of SREBP1 in the two cervical cancer cell lines." (PMID 39425259, 2025). "For example, FASN, which is upregulated in cervical cancer samples, promotes lymph node metastasis via cholesterol reprogramming and lymphangiogenesis." (PMID 40148316, 2025). "Conversely, FASN promotes lymphangiogenesis and metastasis in cervical cancer via the secretion of PDGF-AA/IGFBP3." (PMID 40641601, 2025). "Cervical cancer with pelvic lymph node metastasis has a poor prognosis, and higher LD content accompanied by elevated FASN expression in tumor tissues has been positively related to the lymph node metastasis rate in a mouse model of cervical cancer." (PMID 38500157, 2024). "Inhibiting LD accumulation by a specific FASN inhibitor in a xenograft lymph node metastasis mouse model of cervical cancer significantly decreased tumor size and contributed to a lower incidence of lymph node metastasis." (PMID 38500157, 2024). "FASN promotes lymph node metastasis in cervical cancer via cholesterol reprogramming and lymphangiogenesis." (PMID 39588377, 2024). "It was reported that lipid droplets accumulation promoted cell metastasis in cervical cancer modulated by FASN." (PMID 38693136, 2024). "FASN has been identified as a poor prognostic factor in patients with colon cancer, cervical cancer, cholangiocarcinoma, and clear cell renal cell carcinoma." (PMID 38060103, 2023). "In cervical cancer, studies have utilized gene expression analysis to identify FASN as a potential prognostic or therapeutic target." (PMID 35597782, 2022). "Then, we further explored the expression level of FASN in cervical cancer cell lines and patient samples." (PMID 35597782, 2022). "ETS-related gene and fatty acid synthase signatures were discovered using a multivariate Cox regression model built to identify independent prognostic factors in cervical cancer patients." (PMID 30237984, 2018). "In addition, in cervical cancer, fatty acid synthase (FASN) promotes cisplatin resistance by upregulating SLC7A11, which suppresses ferroptosis." (PMID 40895556, 2025). "In addition, FASN promotes lymph node metastasis via cholesterol reprogramming and lymphangiogenesis in cervical cancer." (PMID 38060103, 2023). "Moreover, loss-of-function and gain-of-function experiments demonstrated the key function of FASN in cervical cancer lymph node metastasis." (PMID 35597782, 2022). "Similarly, patient samples of cervical cancer (n = 28) and normal cervix (n = 16) were applied, the results of which indicated that FASN was highly expressed in CC." (PMID 35597782, 2022). "Genetic targeted therapy or inhibitors based on FASN or this regulatory pathway may shed light on therapeutic options for cervical cancer patients with lymph node metastasis." (PMID 35597782, 2022).